ITGB6 (integrin subunit beta 6)
Diseases named in the same sentence as ITGB6 in open-access papers (continued):
Sharing a sentence is not in itself a finding about the gene and the disease.
colon cancer (9 papers, 2018 to 2024). "A study demonstrates that ITGB6 is expressed in malignant colonic epithelia and is associated with the progression, metastasis, and chemotherapeutic resistance of colon cancer." (PMID 31828095, 2019). "Because of this, some researchers have proposed that ITGB6 can be employed as a new serum biomarker for the detection and evaluation of colon cancer, as well as a marker for tumor monitoring, recurrence, and therapeutic response." (PMID 36186476, 2022). "In a study on colon cancer, immunoliposomes targeting ITGB6 were developed by combining ITGB6 monoclonal antibodies with PEGylated liposomes." (PMID 36293202, 2022). "ITGB6 is significantly increased in the serum of colon cancer, and the level of ITGB6 in the serum of patients after surgery is significantly lower than that before surgery." (PMID 33335550, 2020). "ITGB6 was also considered as a novel serum marker and a highly efficient target for immunoliposome-mediated drug delivery in colon cancer." (PMID 31612115, 2019). "For instance, ITGA11 is overexpressed in colon cancer samples when compared to normal adjacent tissue, while abnormal levels of ITGAV and ITGB6 in colorectal cancer has been associated with epithelial to mesenchymal transition, cancer progression, invasiveness, metastasis and a worse prognosis." (PMID 39167197, 2024). "The combination of ITGB6 and CEA can be used as a marker for postoperative prognosis monitoring of colon cancer." (PMID 33335550, 2020). "The integrin subunit beta 6 protein mRNA (ITGB6) was induced in the two colon cancer cell lines by treatment with MACRO-CM from U937 macrophages, and the colon cancer metastasis-related protein S100A4 mRNA was induced in SW620 cells by treatment with THP-1 MACRO-CM." (PMID 29462209, 2018). "However, we observed elevated expression of ITGB6 (Integrin β6) in sh-UNC5A cells compared with sh-Control cells; ITGB6 is pro-oncogenic and is induced during EMT of colon cancer cells." (PMID 29720215, 2018).
pulmonary fibrosis (9 papers, 2011 to 2023). Chronic progressive interstitial lung disorder characterized by the replacement of the lung tissue by connective tissue, leading to progressive dyspnea, respiratory failure, or right heart failure. "Crucially, we find that loss of Elk1 causes enhanced Itgb6 expression and exaggerated lung fibrosis in an in vivo model of fibrosis, whereas the GR agonist dexamethasone inhibits Itgb6 expression." (PMID 26861876, 2016). "Furthermore, loss of Elk1 in vivo increased levels of Itgb6 mRNA and collagen deposition in a bleomycin model of lung fibrosis." (PMID 26861876, 2016). "Finally, we show that lung tissue from pulmonary fibrosis patients displays reduced Elk1 expression associated with reduced Elk1 binding to the ITGB6 promoter." (PMID 26861876, 2016). "Therefore, to determine whether global loss of Elk1 was sufficient to increase Itgb6 expression in vivo and exacerbate fibrotic responses, we employed the bleomycin model of lung fibrosis." (PMID 26861876, 2016). "In this study, ITGB6 and lung fibrosis-related gene sets are upregulated in SPCY104H-AEC compared with maeSPCY104H-AEC, suggesting that SPCY104H-AEC are in a vulnerable state." (PMID 37701577, 2023). "We have previously demonstrated that ITGB6 mRNA levels are increased in lung tissue homogenates from lung fibrosis patients, which we again found in this study." (PMID 26861876, 2016). "Lungs were harvested 28 days following bleomycin instillation, and then lung fibrosis and Itgb6 mRNA levels were measured." (PMID 26861876, 2016). "For example, multiple genes in the AT1 cell program were closely related to pulmonary veno-occlusive disease (PVOD) (Bmpr2 and Eif2ak4), lung cancer (Itga9 and Braf), pulmonary fibrosis (Cadm1 and Itgb6), pulmonary hypertension (Bmpr2 and Cav1), and pulmonary emphysema (Itgb6)." (PMID 34873160, 2021). "However, whether these mechanisms are involved in up-regulation of ITGB6 in pulmonary fibrosis is unknown." (PMID 26861876, 2016). "In contrast, in the case of molecular target ITGB6 (Integrin-beta 6) from the same screen, the software presented us with an available integrin antagonist compound, GSK3008348, used for an utterly different indication (pulmonary fibrosis), but with successful results." (PMID 36183137, 2022). "αVβ6 integrin (Itgb6) activates latent TGF-β and hence lack of this gene or its inhibition protects against lung fibrosis." (PMID 24204629, 2013).
emphysema (7 papers, 2008 to 2023). "In a similar way, loss of Itgb6 in the lung causes emphysema, mediated by TGF-ß activation and an accumulation of lymphocytes and neutrophils." (PMID 24391734, 2013). "As a classical example, ITGB6 in the integrin family was reported to affect acute lung injury and emphysema by an ITGB6-knockout assay, and ITGB6 exhibited a higher expression in the heat-stress group in this study." (PMID 37587462, 2023). "In accordance, we predicted reduced ITGB6 protein abundance as a potential mechanism contributing to CS-induced emphysema; however, the measured ITGB6 protein abundance in lung homogenates did not change as a result of CS exposure." (PMID 25962837, 2015). "ITGB6 was detected in normal human lung, emphysema lung, and mouse ileum, all known sites of ITGB6 protein expression, whereas the control IgG sections had little or no signal." (PMID 24488487, 2014). "Additionally, ITGB6 is highly expressed in the lungs and the Itgb6 knockout mice exhibited significant airway inflammation, age-related emphysema, and juvenile baldness, that are related to TGF-β1 deficiency." (PMID 37041139, 2023). "Our results have supported neither ITGB6 nor ITGAV as candidate genes for juvenile hairlessness and age dependent emphysema in pigs." (PMID 18549483, 2008).
pancreatic adenocarcinoma (6 papers, 2012 to 2024). "Amongst, increased expressions of LAMB3 and ITGB6 were significantly associated with poor prognosis of patients with pancreatic adenocarcinoma in this study, underlying the importance of the identified enriched pathways in PDAC." (PMID 33194391, 2020). "Comprehensive analysis, together with the pancreatic adenocarcinoma (PAAD) dataset from The Cancer Genome Atlas (TCGA), revealed that the ANTXR1, CMTM6, ITGB6, PIGR, and PTGS2 genes were significantly upregulated in GEM‐resistant PDAC cell lines." (PMID 39488785, 2024). "For example, cholangiocarcinoma (CHOL) overexpresses a large variety of subunits (e.g. ITGAV, ITGA1, ITGA4, ITGA5, ITGA11, ITGB1, ITGB2, ITGB6), whereas, the equally deadly pancreatic adenocarcinoma (PAAD) overexpresses a very limited set of integrins, including ITGA6 and ITGB4." (PMID 30046394, 2018). "We used Gene Expression Omnibus (GEO) database and identified six genes (COL1A2, ITGA2, ITGB6, LAMA3, LAMB3, and LAMC2) that could affect the survival rate of pancreatic adenocarcinoma patients." (PMID 35899199, 2022).
bladder cancer (5 papers, 2019 to 2024). "The integrin family is documented to be involved in various cancer processes (such as tumor initiation, metastasis and drug resistance), and ITGB6 is also reported to be associated with the progression and metastasis of oral squamous cell carcinoma, bladder cancer and colorectal carcinoma." (PMID 34621667, 2021). "Retinoic Acid-Related Orphan Receptor C regulates proliferation, glycolysis, and chemoresistance via the PD-L1/ITGB6/STAT3 signaling axis in bladder cancer." (PMID 37434177, 2023). "Previous studies demonstrated that it could enact these functions through participating in the programmed death ligand-1/integrin β/activator of the transcription 3 (PD-L1/ITGB6/STAT3) signaling pathway in bladder cancer." (PMID 35893817, 2022). "Other studies showed a correlation between a low expression of RORC and a negative correlation with PD-L1 in bladder carcinoma, suggesting the suppression of the PD-L1/ITGB6 pathway." (PMID 39273632, 2024).
cholangiocarcinoma (5 papers, 2018 to 2024). A carcinoma that arises from the intrahepatic biliary tree (intrahepatic cholangiocarcinoma) or from the junction, or adjacent to the junction, of the right and left hepatic ducts (hilar cholangiocarcinoma). "Low expression of ITGB6 in cholangiocarcinoma is associated with poorer prognosis and increased invasiveness." (PMID 36267977, 2022). "Validated with both IHC and RNA-seq, ITGB6 is overexpressed in cervical cancer, liver cancer/cholangiocarcinoma, head and neck cancer, and stomach cancer." (PMID 30046394, 2018). "Furthermore, in our previous study, ITGB4 and ITGB6 mRNA levels in cholangiocarcinoma cell lines were high in HuCCT1; however, almost no expression of either molecule was observed in HuH28, which is known to grow slowly." (PMID 29584696, 2018).
gastric cancer (5 papers, 2018 to 2025). A primary or metastatic malignant neoplasm involving the stomach. "The objective of this study is to explore the association and clinical relevance of Rac1 and ITGB6 expression in gastric cancer." (PMID 38344200, 2024). "By employing the H-score, the expression levels of ITGB6 and Rac1 were determined and compared between gastric carcinoma tissues and adjacent normal tissues within the diagnostic cohort." (PMID 38344200, 2024). "As our previous results demonstrated that serum ITGB6 expression was closely associated with tumor progression in gastric cancer." (PMID 34796117, 2021). "Serum ITGB6 expression was also elevated in gastric cancer patients compared with those healthy volunteers, and elevated serum ITGB6 expression was also associated with lymph node metastasis in the prospective cohort." (PMID 34796117, 2021). "ITGB6 expression in gastric cancer tissues was closely associated with tumor stage, it also served as an independent prognostic indicator for the poor prognosis of gastric cancer." (PMID 34796117, 2021). "In order to evaluate the risk stratification and predict the prognosis of gastric cancer patients, we strongly recommend a routine serum ITGB6 level detection within the perioperative period and during follow-up." (PMID 34796117, 2021). "The present study also showed that serum ITGB6 levels was associated with CEA expression for gastric cancer patients." (PMID 34796117, 2021). "Results showed that serum ITGB6 expression was obviously increased and associated with tumor stage in gastric cancer patients, serum ITGB6 expression was relatively high in patients with liver metastasis." (PMID 34796117, 2021). "It has been demonstrated that positive ITGB6 expression in gastric cancer tissues was linked to significantly reduced survival times." (PMID 34796117, 2021). "Importantly, our study showed that the expression levels of ITGB6 and Rac1 are associated with the unfavorable prognosis of gastric cancer patients." (PMID 38344200, 2024). "For the first time, we demonstrated that serum ITGB6 level may serve as an effective biomarker for the risk stratification and prognostic prediction of gastric cancer patients." (PMID 34796117, 2021). "To explore whether serum ITGB6 expression was associated with ITGB6 expression in tumor tissues, we detected the expression of ITGB6 in gastric cancer tissues using IHC." (PMID 34796117, 2021). "A dramatic decrease of serum ITGB6 expression showed after surgery for most of the enrolled subjects, indicating that serum ITGB6 levels may be associated with tumor burden for gastric cancer patients." (PMID 34796117, 2021). "Importantly, our results showed that serum ITGB6 levels were closely associated with unfavorable prognosis of patients with gastric cancer." (PMID 34796117, 2021). "The present study demonstrated that patients with a serum ITGB6 level >0.5ng/ml were highly suspected to have lymph node metastasis or distant metastasis, indicating that ITGB6 might serve as a potential marker for the risk stratification of gastric cancer patients." (PMID 34796117, 2021). "The gastric cancer cell line 7901 was cultured and the expression of ITGB6 was downregulated by transfection with ITGB6 interfering RNA." (PMID 38344200, 2024). "And vice versa, inhibiting the activity of Rac1 results in decreased proliferation, invasion, and metastasis capabilities of gastric cancer cells expressing ITGB6." (PMID 38344200, 2024). "To conclude, our study findings indicate that the levels of ITGB6 and Rac1 are heightened in gastric carcinoma and exhibit a correlation, thereby linking them to tumor advancement and unfavorable prognosis among gastric cancer patients." (PMID 38344200, 2024). "Subsequently, CCK8 experiments were used to investigate changes in cell activity after ITGB6 interference, and it was found that downregulation of ITGB6 can significantly inhibit gastric cancer cell activity." (PMID 38344200, 2024).
gastric cancer (continued). "Classifying the diagnostic cohort based on this threshold, 198 individuals suffering from gastric cancer were partitioned into categories of high and low ITGB6 expression." (PMID 38344200, 2024). "To further validate this effect, we treated gastric cancer cell lines transfected with NC, si-ITGB6, and NSC23766." (PMID 38344200, 2024). "Transwell migration and invasion experiments (with Matri-gel) were conducted to explore the effects of si-ITGB6 and Rac1 inhibitor on the migration and invasion ability of gastric cancer cells." (PMID 38344200, 2024). "The present study investigate the expression and correlation of ITGB6 and Rac1 proteins in gastric cancer tissues." (PMID 38344200, 2024). "Both the Kaplan-Meier survival analysis and Cox regression model analysis demonstrated that the presence of positive expression of ITGB6 and Rac1 proteins served as independent prognostic factors for gastric cancer." (PMID 38344200, 2024). "Immunostaining was conducted to ascertain the expression of ITGB6 and Rac1 in gastric carcinoma specimens in comparison to neighboring normal tissues." (PMID 38344200, 2024). "Correlation between serum ITGB6 expression and clinical characteristics of patients with gastric cancer." (PMID 34796117, 2021). "Results showed that the OS of gastric cancer patients with high expression of ITGB6 was 66.7%, which was lower than those patients with low expression of ITGB6 (90.5%)." (PMID 34796117, 2021). "Consistent with previous findings, elevated ITGB6 protein expression was also shown in gastric cancer tissues compared with adjacent normal tissues." (PMID 34796117, 2021). "By analyzing TCGA and GTEx public available database, we found that the mRNA expression level of ITGB6 in gastric cancer was significantly increased compared with that in normal tissues." (PMID 34796117, 2021). "Focusing on risk stratification, prognostic prediction and recurrence surveillance, we explored the clinical significance of serum ITGB6 levels for gastric cancer patients by both retrospective and prospective cohorts." (PMID 34796117, 2021). "Results showed that serum ITGB6 levels decreased dramatically after surgery for most of advanced gastric cancer patients." (PMID 34796117, 2021). "In the present study, a retrospective cohort with 135 gastric cancer patients and a prospective cohort with 34 gastric cancer patients were constructed, ITGB6 expression were detected in both the serum specimens and the tissue specimens." (PMID 34796117, 2021). "A nomogram including ITGB6 expression was also constructed and validated to predict the prognosis of gastric cancer patients." (PMID 34796117, 2021). "Then we explored the prognostic value of serum ITGB6 expression in overall survival (OS) of gastric cancer patients." (PMID 34796117, 2021). "Although the sample size was limited, further research focusing on the role of ITGB6 in liver metastasis of gastric cancer is warranted." (PMID 34796117, 2021). "ITGB6 and Rac1 are indicators of poor prognosis and tumor progression in gastric cancer patients." (PMID 38344200, 2024). "In addition, in vitro experiments including CCK8 and Transwell assays were conducted to explore the roles of ITGB6 and Rac1 in gastric cancer." (PMID 38344200, 2024). "It was found that downregulation of ITGB6 expression and Rac1 activity inhibition could significantly inhibit the migration and invasion ability of gastric cancer cells." (PMID 38344200, 2024). "However, the prognostic implications of ITGB6 and Rac1 overexpression in gastric cancer patients, as well as their potential interrelationship, remain indeterminate." (PMID 38344200, 2024). "To explore whether ITGB6 could be detected in the serum of gastric cancer patients, we investigated serum ITGB6 levels in a retrospective cohort containing 135 gastric cancer patients." (PMID 34796117, 2021). "Previous studies have demonstrated that ITGB6 was involved in the progression of gastric cancer." (PMID 34796117, 2021).